RBM24 (RNA binding motif protein 24)
Description:
Multifunctional RNA-binding protein involved in the regulation of pre-mRNA splicing, mRNA stability and mRNA translation important for cell fate decision and differentiation. Plays a major role in pre-mRNA alternative splicing regulation. Mediates preferentially muscle-specific exon inclusion in numerous mRNAs important for striated cardiac and skeletal muscle cell differentiation. Binds to intronic splicing enhancer (ISE) composed of stretches of GU-rich motifs localized in flanking intron of exon that will be included by alternative splicing (By similarity). Involved in embryonic stem cell (ESC) transition to cardiac cell differentiation by promoting pre-mRNA alternative splicing events of several pluripotency and/or differentiation genes. Plays a role in the regulation of mRNA stability. Binds to 3'-untranslated region (UTR) AU-rich elements in target transcripts, such as CDKN1A and MYOG, leading to maintain their stabilities. Involved in myogenic differentiation by regulating MYOG levels. Binds to multiple regions in the mRNA 3'-UTR of TP63 isoform 2, hence inducing its destabilization. Also promotes the destabilization of the CHRM2 mRNA via its binding to a region in the coding sequence. Plays a role in the regulation of mRNA translation. Binds to a huge amount of mRNAs. Required for embryonic heart development, sarcomer and M-band formation in striated muscles (By similarity). Together with RBM20, promotes the expression of short isoforms of PDLIM5/ENH in cardiomyocytes (By similarity). (Microbial infection) Promotes hepatitis C virus (HCV) replication over translation through the inhibition of viral protein expression. Decreases viral translation by linking viral 5'- and 3'-UTRs, blocking 80S ribosome assembly on the viral IRES and enhancing the interaction of the mature core protein and 5'-UTR.
Synonyms: RNPC6; FLJ30829; dJ259A10.1
Tractability: PROTAC: ubiquitination databases record sites on it.
Gene: Protein-coding gene on chromosome 6 (17,281,361 to 17,293,871, forward strand). Ensembl gene ENSG00000112183.
Subcellular location: Nucleus; Cytoplasm
Subcellular location (Human Protein Atlas): Nucleoplasm; Cytosol
Gene Ontology:
Molecular function: mRNA 3'-UTR AU-rich region binding; mRNA 3'-UTR binding; mRNA CDS binding; protein binding; sequence-specific mRNA binding; pre-mRNA intronic binding; nucleic acid binding; RNA binding
Biological process: 3'-UTR-mediated mRNA destabilization; DNA damage response; mRNA destabilization; mRNA stabilization; negative regulation of cytoplasmic translation; positive regulation of 3'-UTR-mediated mRNA stabilization; positive regulation of myotube differentiation; positive regulation of stem cell differentiation; regulation of alternative mRNA splicing, via spliceosome; positive regulation of myoblast differentiation; positive regulation of skeletal muscle fiber differentiation; regulation of mRNA stability; regulation of myotube differentiation; endocardial cushion development
Cellular component: cytosol; nucleoplasm; cytoplasm; nucleus
Genetic constraint (gnomAD): Loss-of-function variants: 5 observed, 17.18 expected, observed/expected ratio (o/e) 0.29, 90% interval 0.15 to 0.61. The upper end of that interval is the gene's LOEUF score, 0.61, which puts it in group 2 of 6, group 1 being the genes least tolerant of losing a copy. Missense variants: 232 observed, 274.29 expected, observed/expected ratio (o/e) 0.85, 90% interval 0.76 to 0.94. Synonymous variants: 143 observed, 121.5 expected, observed/expected ratio (o/e) 1.18, 90% interval 1.03 to 1.35.
Homologues: Orthologues: chimpanzee RBM24 (100% identical), guinea pig RBM24 (99% identical), dog RBM24 (99% identical), mouse Rbm24 (99% identical), rat Rbm24 (98% identical), tropical clawed frog rbm24 (90% identical), zebrafish rbm24a (83% identical), rabbit RBM24 (78% identical), zebrafish rbm24b (77% identical), macaque RBM24 (75% identical). Paralogues in human: RBM38 (69% identical), PABPC1 (26% identical), RBMS1 (26% identical), PABPC4 (25% identical), ELAVL2 (25% identical), RBMS2 (25% identical), RBMS3 (25% identical), PABPC3 (24% identical), PABPC1L (24% identical), ELAVL4 (23% identical), SYNCRIP (23% identical), ELAVL3 (22% identical), and 12 more.
Diseases named in the same sentence as RBM24 in open-access papers:
RBM24 is named in the same sentence as 48 diseases in open-access papers, as found by Europe PMC text mining. Sharing a sentence is not in itself a finding about the gene and the disease. The quoted sentences say what the papers report.
cardiomyopathy (10 papers, 2015 to 2023). A disease of the heart muscle or myocardium proper. "Both in zebrafish and mice, loss of Rbm24 function causes disrupted Z-discs and sarcomere organization due to a decreased expression of sarcomeric proteins, a phenotype reminiscent of cardiomyopathy." (PMID 32806768, 2020). "As RBM24 was already established as a major regulator of muscle-specific alternative splicing we analyzed the coding sequence of three RBM24-splice variants (NM_001143942, NM_153020, NM_001143941) in 190 cardiomyopathy index patients by Sanger sequencing." (PMID 30421357, 2019). "In summary, it remains an open question if RBM24 can be established as a rare cardiomyopathy associated gene." (PMID 30421357, 2019). "Similarly, RNA-binding motif protein 24 (RBM24) regulates a subset of genes associated with cardiomyopathies such as sarcomere z-disc genes TTN, nebulette (NEBL), and enah actin regulator (ENAH)." (PMID 38132114, 2023). "Indeed, as presented above, loss of Rbm24 in mice causes cardiomyopathy, but overexpression of Rbm24 has been shown to induce cardiac fibrosis in the mouse model by promoting collagen synthesis." (PMID 32806768, 2020). "Although we cannot exclude that in further specific cases pathogenic RBM24 mutations might be found, our data suggest that RBM24 mutations are rare in human cardiomyopathy patients." (PMID 30421357, 2019). "Knockout of RBM24 resulted in misregulation of these splicing transitions which contributed to the subsequent development of cardiomyopathy." (PMID 30267374, 2019). "This furthers our understanding of the regulatory mechanism of cardiac sarcomere assembly in both physiologic and pathologic contexts, and uncovers a potential novel pathway to cardiomyopathy through modulating the Stk38/Rbm24 protein activity." (PMID 28322254, 2017). "Consequently, other RNA-binding proteins such as CELF-3, CELF-5, RBM24, RBM25 and LUC7L3 have been linked to the development of cardiomyopathies." (PMID 26116573, 2015). "It remains an open question whether human RBM24 is a cardiomyopathy-associated gene, since no mutations in the three main isoforms of RBM24 have been identified in DCM patients." (PMID 33757121, 2022). "A commentary on this study evidenced that RBM24 mutations in human cardiomyopathy patients might be a rare event due to the absence of RBM24 mutations associated with human disease." (PMID 32276354, 2020). "Although RBM24 has not (yet) been identified as a clinically relevant disease gene for human DCM7,35, our finding of altered sarcomere slack length in Rbm24 haploinsufficient mice does indicate that it is conceivable that pathogenic variants in RBM24 underlie human cardiomyopathy in some cases." (PMID 32376900, 2020).
heart failure (7 papers, 2017 to 2024). Inability of the heart to pump blood at an adequate rate to meet tissue metabolic requirements. "Although the involvement of RBM24 in human heart disease remains to be determined, there is evidence showing the up-regulation of RBM24 in heart failure, which is associated with fetal-specific gene expression and protein isoform switching." (PMID 38535111, 2024). "RBM24, which has been associated with dilated cardiomyopathy, one common cause of heart failure, was also overexpressed in heart failure." (PMID 35226669, 2022). "Alternatively, it is well possible that aberrant RBM24 levels or mutations in RBM24, can affect disease progression in acquired heart disease or disease penetrance in genetic forms of heart failure." (PMID 32376900, 2020). "Defects in the splicing factor that are pertinent to regulating cardiac-related genes such as hnRNP H, hnRNP U, RBM24 and tra2β are known to cause heart failure." (PMID 28077597, 2017). "Therefore, we believe further studies relating RBM24 to familial forms of DCM or heart failure progression are needed." (PMID 32376900, 2020). "Indeed, it is suggested that, similar to the loss of Rbm24, aberrant splicing due to the dysregulated expression of MBNL and QKI could contribute to the disease mechanism underlying the pathogenesis of heart failure." (PMID 38535111, 2024). "Here, we report that cardiac-specific ablation of RBM24 at postnatal stage leads to rapidly progressive DCM and heart failure." (PMID 30267374, 2019). "In this paper, using conditional RBM24 knockout mice, we demonstrated that ablation of RBM24 in postnatal heart led to rapidly progressive dilated cardiomyopathy (DCM), heart failure, and postnatal lethality." (PMID 30267374, 2019). "Previous studies have determined heart-specific RBPs (RBM20, RBM24, HuR, etc.)that were not included in our heart failure-specific RBPs." (PMID 36313471, 2022). "Our data not only offer mechanistic insights but also provide functional annotation of RBM24 splicing targets that contribute to DCM and heart failure, highlighting the key role of post-transcriptional regulation in physiological cardiac function and pathogenesis." (PMID 30267374, 2019). "Notably, our analysis identified RBM24 as a splice factor that determined the splicing switch of a subset of genes in the sacomeric Z-disc complex, including Titin, the major disease gene of DCM and heart failure." (PMID 30267374, 2019).
nasopharyngeal carcinoma (7 papers, 2016 to 2022). A carcinoma arising from the nasopharyngeal epithelium. "As in prostate cancer and nasopharyngeal carcinoma, Rbm24 also interacts with microRNAs in other tissues to maintain cellular homeostasis." (PMID 32806768, 2020). "It has been also shown that in nasopharyngeal carcinoma, the expression of Rbm24 is reduced, which leads to the down-regulation of miR-25 that has the ability to suppress cell proliferation by targeting the pro-oncogenic lncRNA MALAT1." (PMID 32806768, 2020). "Although the role of RBM24 as a carcinoma inhibitor gene has been demonstrated in NPC (nasopharyngeal carcinoma), CRC (colorectal cancer), and hepatic carcinoma, its precise function in HSCC is elusive." (PMID 36213838, 2022). "In addition, RBM24 was reported to suppress nasopharyngeal cancer progression." (PMID 34021255, 2021). "Studies have discovered that RNA-binding protein 24 (RBM24) is oftentimes downregulated in nasopharyngeal carcinoma (NPC)." (PMID 33758106, 2021). "In this study, we found that RNA-binding protein 24 (RBM24) was frequently downregulated in nasopharyngeal carcinoma (NPC)." (PMID 27584791, 2016). "Expression profiling indicates that RBM24 and CELF4 are among the few RBPs that show frequent downregulation in nasopharyngeal carcinoma (NPC) tumor tissues and various NPC cell lines." (PMID 35406615, 2022). "In nasopharyngeal carcinoma (NPC) cell lines, analysis of microRNA (miRNA) expression profiles induced by RBM24 indicates that miR-25 represents the most upregulated gene and mediates the tumor suppressor function of RBM24." (PMID 35406615, 2022). "RBM24 (RNA binding motif 24) has not been described in breast cancer, but this gene was characterized to suppress nasopharyngeal carcinoma progression." (PMID 30678243, 2019).
bladder cancer (5 papers, 2021 to 2024). "Other studies have shown that high RBM24 expression is associated with a poor prognosis in 32 patients with bladder cancer via the Runx1t1/TCF4/miR-625–5p positive feedback loop." (PMID 39132499, 2024). "The enhancement of RUNX1T1 mRNA causes a cascade reaction of the loop, causing RBM24 upregulation, further promoting bladder cancer progression." (PMID 35902872, 2022). "It is also implicated in carcinogenesis, but the functions of RBM24 in bladder cancer (BC) remain unclear." (PMID 34021255, 2021). "RBM24 has been shown to display increased expression in bladder cancer tissues and appears to play an oncogenic role by promoting cell proliferation." (PMID 35406615, 2022). "Recent studies show that by binding to the 3′-UTR, RBM24 stabilizes RUNX1T1 (RUNX1-related transcription factor 1) mRNA in bladder carcinoma and PTEN (phosphatase and tensin homolog) mRNA in colorectal cancer (CRC), with opposite effects on tumor progression." (PMID 35406615, 2022). "A protein called RBM24 promotes progression of bladder cancer (BC) by forming a positive feedback loop with a specific transcription factor, driving cancer cell proliferation." (PMID 34021255, 2021). "This positive feedback loop may represent a mechanism by which RBM24 participates in bladder cancer progression, but in vivo functional assays will be necessary to further determine its implication in tumor growth." (PMID 35406615, 2022). "RBM24 promotes the proliferation of bladder cancer cells in vitro." (PMID 34804951, 2021). "Several RBM proteins have been studied in the context of bladder cancer, including RBM3, RBM10, RBM24, RBM5, and RBMX." (PMID 39132499, 2024). "RUNX1T1 is also involved in the progression of bladder cancer via the positive RUNX1T1/TCF4/miR-625-5p feedback loop, closely relating to RNA-binding motif protein 24 (RBM24), a determinant of carcinogenesis." (PMID 35902872, 2022). "Functional analyses using human bladder carcinoma cells indicate that RBM24 stabilizes RUNX1T1 mRNA and increases the expression of RUNX1T1 protein, which in turn positively regulates RBM24 expression by suppressing the transcription of its inhibitory miR-625-5p." (PMID 35406615, 2022).
dilated cardiomyopathy (5 papers, 2019 to 2025). Cardiomyopathy which is characterized by dilation and contractile dysfunction of the left and right ventricles. "RBM24 loss destroys global alternative splicing and contributes to dilated cardiomyopathy." (PMID 36313471, 2022). "Additionally, cardiac-specific knockout of RBM24 in mice led to dilated cardiomyopathy due to misregulation of AS in multiple contractile genes." (PMID 41214391, 2025).
breast carcinoma (3 papers, 2017 to 2024). "Our work shows for the first time that the RBM24 gene is significantly upregulated by E2, zearalenone and apigenin (p < 0.001), suggesting that RBM24 may be a new ER target gene in breast cancer." (PMID 30678243, 2019). "Conversely, in the domain of breast cancer, an elevated expression of RUNX1T1 facilitates RBM24‐induced tumour cell proliferation, thereby fostering tumour progression." (PMID 38894657, 2024).
head and neck squamous cell carcinoma (3 papers, 2021 to 2022). A squamous cell carcinoma that arises from any of the following anatomic sites: lip and oral cavity, nasal cavity, paranasal sinuses, pharynx, larynx, and salivary glands. "Three RBP genes (NOVA1, EZH2, and RBM24) were identified as central genes related to the prognosis of head and neck squamous cell carcinoma (HNSCC)." (PMID 33711033, 2021). "Several members of RRM family have been reported to play vital role in cancer metastasis, and a bioinformatics study based on data from TCGA database suggested RBM24 might be a prognostic-related gene in head and neck squamous cell carcinoma." (PMID 36213838, 2022). "For example, survival analyses suggest that RBM24 may be a potential prognostic biomarker for head and neck squamous cell carcinoma (HNSCC) and skin cutaneous melanoma (SKCM) patients." (PMID 35406615, 2022).
hepatocellular carcinoma (3 papers, 2018 to 2023). A malignant tumor that arises from hepatocytes. "In HBV-transfected hepatoma cell lines, both knockdown and overexpression of RBM24 led to decreased HBV replication and transcription." (PMID 29760415, 2018).
microphthalmia (3 papers, 2020 to 2021). Congenital or developmental anomaly in which the eyeballs are abnormally small. "Consistent with SOX2′s known role in microphthalmia and anophthalmia in human patients, knockdown and knockout Rbm24-deficient mice and zebrafish often displayed eye defects including microphthalmia and/or anophthalmia." (PMID 33494192, 2021). "Although both zebrafish and mouse Rbm24 mutants display the microphthalmia phenotype, this seems to be indirectly caused by the absence of blood supply because the rescue of blood circulation in the zebrafish mutants prevents microphthalmia but not cataract formation." (PMID 32806768, 2020).
cardiac hypertrophy (2 papers, 2022 to 2024). "It is reasonable to speculate that the cooperatively regulating RBM20 and RBM24 may affect myocardial stiffness, because cardiac hypertrophy is closely related to wall stiffness and compliance, but the mechanisms remain unknown." (PMID 35783855, 2022). "Although Rbm20 or Rbm24 individually display weak or no activity on Enh splicing, they cooperate to promote expression of the Enh3 and Enh4 isoforms of Enh, which lack the LIM domain and function to repress cardiac hypertrophy." (PMID 38535111, 2024). "In addition, promoting RBM20 and RBM24 increased the expression of ENH subtypes lacking LIM domains (such as ENH3 and ENH4), thus prevented myocardial hypertrophy in mice." (PMID 35783855, 2022).
colon carcinoma (2 papers, 2017 to 2022). "Accordingly, in patient-derived colon cancers stratified according to their consensus molecular signature, the same QKI, RBM24, and MBNL2 genes were found to have increased expression in CMS4 tumors, known for their pronounced mesenchymal composition and poor prognosis." (PMID 36346211, 2022). "Despite previous reports showing that the p21 mRNA transcript is stabilized by both Rbm24 and Rbm38 in breast- and colon carcinoma cell lines, we did not observe reduced p21 mRNA levels in Rbm38 -/- hearts." (PMID 28850611, 2017).
colorectal adenoma (2 papers, 2021 to 2022). An adenoma that arises from the colon or rectum. "One study demonstrates that RBM24 expression is strongly downregulated in colorectal tumor tissues from human patients and that spontaneous colorectal adenomas appear in RBM24-knockout mice." (PMID 35406615, 2022). "RBM24 expression in colorectal adenoma tissues of Apcmin/+ mouse was downregulated compared with adjacent normal samples and was positively correlated with PTEN expression." (PMID 34709758, 2021). "Data indicated that Rbm24 knockout promoted the proliferation of colorectal epithelial cells in mice, increased intestinal length and facilitated the development of colorectal adenomas in mice." (PMID 34709758, 2021). "Rbm24‐knockout mice developed spontaneous colorectal adenomas with lower expression of phosphatase and tensin homolog (PTEN)." (PMID 34709758, 2021). "RBM24 expression in human colorectal specimens and mouse colorectal adenoma tissues was significantly lower than in controls." (PMID 34709758, 2021). "Rbm24‐knockout mice develop spontaneous colorectal adenomas." (PMID 34709758, 2021).
colorectal tumor (2 papers, 2021 to 2022). "Taken together, RBM24 expression is markedly lower in colorectal tumours than in para‐carcinoma tissues." (PMID 34709758, 2021).
fibrosis (2 papers, 2018 to 2022). the formation of excess fibrous connective tissue in an organ or tissue in a reparative or reactive process. "Conversely, AAV9-mediated RBM24 overexpression reportedly led to cardiac fibrosis in adult mice, possibly by regulating the TGFβ signaling pathway." (PMID 36233241, 2022). "Overall, we show that increased expression of Rbm24 in the early postnatal and adult mouse heart increases cardiac fibrosis." (PMID 30076363, 2018).